ASS1 (argininosuccinate synthase 1)
Diseases named in the same sentence as ASS1 in open-access papers (continued):
Sharing a sentence is not in itself a finding about the gene and the disease.
tumor (continued). "Previous studies have shown that ASS1 expression inhibits fibroblast proliferation, and ASS1 loss with consequent arginine auxotrophy has been observed in multiple tumor types; conversely, ASS1 overexpression suppresses tumor growth and promotes apoptosis." (PMID 41350286, 2025). "In vivo, it suppressed tumor tissue arginine metabolism, slowed allograft tumor growth, and decreased ASS1 expression." (PMID 41304979, 2025). "Of note, tumor cells evolved to favor the shunting of aspartate to nucleotide instead of arginine synthesis following silencing of ASS1." (PMID 40253325, 2025). "High ASS1 protein expression in GC tissue is positively correlated with aggressive tumour phenotype and unfavourable prognosis, supporting the utility of ASS1 as a useful prognostic marker for GC." (PMID 41154605, 2025). "On the other hand, in the OE-AR-ASS1P3 model, it seems that the AR blocked ASS1P3’s sponging ability, allowing miR-34a-5p interaction and the inhibition of ASS1, therefore increasing tumor growth." (PMID 39585048, 2024). "To further reveal the mechanism of the tumor suppressor function of ASS1 in TNBC, we conducted coimmunoprecipitation assays followed by LC‒MS/MS analysis in 293 T cells to identify potential proteins that interact with ASS1." (PMID 38710705, 2024). "Conversely, OE-ASS1P3 showed a reduced tumor size and weight, aligning with its function as a sponge for miR-34a-5p oncogene, subsequently enhancing the expression and activity of ASS1." (PMID 39585048, 2024). "ASS1 downregulation redirects aspartate from urea production towards pyrimidine biosynthesis, facilitating the high demand of rapid tumor proliferation." (PMID 38218942, 2024). "Several reports have shown that ASS1 is underexpressed in a range of tumors and functions as a tumor suppressor." (PMID 38710705, 2024). "Enzymes required for the endogenous synthesis of arginine by tumor cells include argininosuccinate synthase 1 (ASS1), argininosuccinatelyase (ASL) and ornithine carbamoyl transferase (OCT)." (PMID 39239650, 2024). "Tumor cells will prefer to use their consumption of arginine, and most tumors lack argininosuccinate synthetase 1 (ASS1)." (PMID 39596288, 2024). "Recent studies have additionally highlighted the significance of decreased ASS1 activity in promoting tumour growth." (PMID 39175990, 2024). "Argininosuccinate synthase 1 (ASS1) expression showed a negative correlation to tumour staging, indicating a reduced ASS1 expression during tumour progression." (PMID 39175990, 2024). "ASS1 knockout and knockdown resulted in increased serine synthesis as well as tumor growth through stabilization of PHGDH protein levels, and this effect was significantly abrogated by PHGDH knockout." (PMID 38710705, 2024). "In ccRCC, the repression of urea cycle enzymes, arginase 2 and argininosuccinate synthase 1, promotes tumor growth in part by conserving PLP." (PMID 37682999, 2023). "Most tumor cells lack argininosuccinate synthetase 1 (ASS1), which is a key enzyme that produces arginine." (PMID 37367892, 2023). "Currently, several potential biomarkers have been proposed, including levels of tumor proteins such as ASS1, HIF-1, and WWOX." (PMID 37445845, 2023). "It is possible that high levels of ASS1 support tumor proliferation and aggressiveness through increased arginine, which translates into increased nitric oxide (NO) production." (PMID 37762133, 2023). "iNKT upregulate LAT-1/ ASS1 in low arginine environments leading to activation of antigen-specific T cells and tumour clearance." (PMID 35962843, 2023). "Both arginine and its synthesis-related ASS1 gene are up-regulated in tumor tissues (Fig. 3a5, a7, b3)." (PMID 37164975, 2023). "ASS1 levels are increased in various tumor types and restricting arginine metabolism by the diet or arginine catabolizing agents can be effective." (PMID 37290438, 2023).
tumor (continued). "Understanding the interaction of immune cells and ASS1-expressing tumor cells in the microenvironment is important for predicting immunotherapeutic efficacy and potential resistance mechanism." (PMID 38053661, 2023). "In the context of microenvironmental arginine deprivation, ASS1 and arginine biosynthesis can switch their role to become tumor supportive." (PMID 37254839, 2023). "In this research, we reported the relationship between ASS1 gene alteration and the survival prognosis of different tumor types." (PMID 38053661, 2023). "Further, we combined all tumor expression data from TCGA using the GEPIA2 tool to obtain the top 100 genes interacting with ASS1." (PMID 38053661, 2023). "The tumor H-score distribution defined three groups as ASS1 low (ASS1L), moderate (ASS1M), or high (ASS1H)." (PMID 36669126, 2023). "Arginine is a semi-essential amino acid involved in tumor growth, which can be synthesized by the enzyme argininosuccinate synthase 1 (ASS1)." (PMID 37445594, 2023). "It was reported that miR-34a-5p negatively regulated ASS1, while lncRNA 00312 played an anti-tumor role in vitro by down-regulating miR-34a-5p and up-regulating ASS1." (PMID 36969848, 2023). "The CEACAM5, HMGB3, and ASS1 genes were specifically expressed in tumor cells from the tumor sample groups (tLung, tL/B, mLN, and mBrain)." (PMID 36397035, 2022). "Under acidic and hypoxic conditions, it has been demonstrated that hypoxia inducible factor alpha (HIF1α) binds to ASS1 and downregulates the expression levels of ASS1, providing tumor cells with a metabolic advantage for survival." (PMID 35910381, 2022). "In vivo experiments further validated that PGAM1 promoted tumor growth in BC by altering ASS1 expression." (PMID 35674458, 2022). "In arginase-treated cells, the expression of ASS1 is restored and up-regulated, allowing arginine-deprived tumor cells to recover endogenous arginine synthesis." (PMID 35814439, 2022). "The expression of ASS1 is varied in different types of tumors; further, the expression of ASS1 is heterogenous even within the same tumor, reflecting tumor heterogeneity." (PMID 35898872, 2022). "In a word, the anti-tumor effect of tadalafil on CRC is the result of multiple factors including tumor suppressor gene ASS1 and metabolic intermediates, such as succinate and L-glutamine." (PMID 35694253, 2022). "Given the importance of arginine in cellular processes of tumors, making the overexpression of ASS1 in tumor cells suppresses cell growth, and arginine deprivation became a highly promising therapeutic strategy." (PMID 35694253, 2022). "Numerous studies have shown that tumoral ASS1 functions as a tumor suppressor to sustain the anti-tumor function in a wide variety of tumors." (PMID 35910381, 2022). "A recent study reported that, in an arginine-restricted TME, tumor cells and T cells exhibit distinct states based on Argininosuccinate synthetase 1 (ASS1) expression." (PMID 36231064, 2022). "Specifically, ASS1 overexpression effectively inhibits tumor growth by activating PERK/eIF2α/ATF4/CHOP axis in Huh7 and SNU475 cells, indicating upregulating tumoral ASS1 expression as a promising strategy in tumors with low ASS1 expression." (PMID 35910381, 2022). "In gastric cancer, ASS1 knockdown leads to impaired tumor cell invasion by promoting autophagy-lysosome machinery to degrade Snail and Twist." (PMID 35910381, 2022). "It is worth noticing that ASS1 silencing is resulted from the epigenetic silencing of the ASS1 promoter via methylation of the CpG islands, which has been observed in multiple tumor types." (PMID 35910381, 2022).
tumor (continued). "We found that Arg2 is the main metaboliser in 88% of MB tumours and that these were deficient in recycling enzymes ASL, ASS1, and OTC in 79%, 88%, and 85% of cases." (PMID 35782058, 2022). "The IHC staining further confirmed that ASS1 was highly expressed in parenchyma cells in non-tumor tissues but reduced in HCC tissues while p-CAD expression was significantly elevated in HCC tissues." (PMID 35864952, 2022). "Western blot analyses of ASS1 and phosphorylated CAD (p-CAD) in 12 paired clinical samples revelated that compared to non-tumor liver samples, ASS1 was notably downregulated, whereas CAD activation (p-CAD/CAD ratio) was upregulated in HCC tissues." (PMID 35864952, 2022). "In this study, we revealed a new mechanism whereby the tumor cells regain the expression of ASS1 by the knockdown of PGAM1." (PMID 35674458, 2022). "In renal cellular carcinoma, loss of ASS1 and ASL makes aspartate flux towards pyrimidine synthesis to support tumor proliferation." (PMID 35910381, 2022). "ASS1-low tumor cells become very dependent on external arginine, forming the basis of arginine deprivation therapy." (PMID 35265615, 2022). "In contrast to its tumor-inhibiting effects, ASS1 has a pro-tumor role in tumor proliferation and metastasis, and the mechanisms seem to vary and differ depending on the specific type of tumor." (PMID 35910381, 2022). "It has been well-established that the re-expression of ASS1 is a main reason for tumor resistance to ADI-PEG20." (PMID 35910381, 2022). "Similar result was obtained in pLGG with 96%, 93%, and 91% of tumours being deficient in ASL, ASS1, and OTC, respectively." (PMID 35782058, 2022). "Tumoral expression levels of ASS1 are also regulated when encountering external factors from the tumor microenvironment to metabolically benefit tumor cell survival." (PMID 35910381, 2022). "Several studies showed that overexpression of ASS1 in tumor cells suppresses cell growth and ASS1 behaves as a tumor suppressor." (PMID 34298755, 2021). "To confirm that SPA and LM-2I -induced tumor inhibition is indeed via targeting ASS1, we established ASS1 stable knockout (ASS1-KO) MDA-MB-231 cells by using CRISPR/Cas9 system." (PMID 33859183, 2021). "Whilst tumour cells can metabolically adapt to arginine deprivation by upregulating ASS1 in an ATF4 and CEBPβ-dependent manner, T lymphocytes become dysfunctional in this context." (PMID 34637000, 2021). "The tumor-specific suppression of ASS1 is thought to divert aspartate, the precursor for intracellular arginine, for nucleotide synthesis needed for rapid cell growth." (PMID 33664852, 2021). "All tumor spheroids of the eight Korean patients displayed significantly lower ASS1 mRNA expression than in spheroids of normal hepatocytes." (PMID 33838671, 2021). "ASS1 is differentially expressed across a wide range of tumors, the effects of which also differ in each type of tumor." (PMID 33838671, 2021). "One possible explanation is that ASS1 diverts aspartate to arginine synthesis from pyrimidine/purine synthesis which is much needed for tumor cells." (PMID 34298755, 2021). "ADI treatment or arginine starvation effectively kills ASS1-low tumor cells via different mechanisms, including caspase-dependent apoptosis or caspase-independent autophagic death." (PMID 33893278, 2021). "Our study here uncovers two potential metabolic tumor suppressors in ccRCC—the urea cycle enzymes ASS1 and ASL." (PMID 34861885, 2021). "SPA and its derivative LM-2I specifically target and bind to ASS1 at the 97th cysteine site in tumor cells, leading to significantly enhanced ASS1 enzymatic activity and tumor inhibitory effect." (PMID 33859183, 2021). "Taken together, our data suggests that ASS1 and ASL act as potential metabolic tumor suppressors in ccRCC, and their loss conserves cellular aspartate pools and regulates nitric oxide generation to give ccRCC cells a proliferative edge." (PMID 34861885, 2021).
tumor (continued). "Accumulating evidence supports that SCLC cells are auxotrophic for arginine meaning that tumor cells are unable to synthesize it and are dependent on extracellular arginine because of the lack or low expression of argininosuccinate synthetase 1 (ASS1)." (PMID 34958428, 2021). "This is particularly important for ASS1 overexpressor, as ASS1 has been shown to be a tumor suppressor that suppresses AKT signals 20 and diverts aspartate to arginine synthesis thus diminishing the nucleotide pool and inhibiting cell growth." (PMID 33664852, 2021). "While ASS1 was found to be downregulated in GBM tumours and NCH644 NS cultures, the expression of ODC1, SLC25A13 and SLC25A15 was increased." (PMID 33809510, 2021). "Tumor cells often augment pyrimidine synthesis by suppressing arginine synthesis via epigenetic silencing of ASS1, the basis of arginine-deprivation therapy." (PMID 34298755, 2021). "Most tumor cells lack ASS1 (argininosuccinate synthetase 1), a key enzyme that produces arginine, and therefore will cause the loss of intracellular arginine synthesis capacity." (PMID 33546704, 2021). "In CT26 tumor cells group where Bcl9 was knocked down by shRNA, Rgs5, Dmkn, and Ass1 were highly expressed." (PMID 34026600, 2021). "This is consistent with recent work showing that ASS1-expressing CAR-T cells are more effective at targeting tumor cells in vivo, suggesting a potential therapeutic strategy to rescue T cell growth in arginine-depleted patients." (PMID 33979616, 2021). "Due to its relevance to cancer therapy, we utilized ASS1-low tumor cells, CWR22Rv1 and PC3, addicted to external arginine as our models." (PMID 33893278, 2021). "Here, we found that bidirectional interactions between ASS1 ER stress responses in HCC-derived multicellular tumor spheroids can limit HCC progression." (PMID 33838671, 2021). "The two groups with differential ASS1 expression exhibited significant differences in 10-year survival rates after resection that were significantly higher when ASS1 expression was higher in tumor vs. peritumoral tissues." (PMID 33838671, 2021). "In this study, we show that tumor cells synthesize arginine from citrulline by upregulating argininosuccinate synthetase 1 (ASS1)." (PMID 33979616, 2021). "It is possible that high levels of ASS1, which can result in high levels of argininosuccinate, support tumor proliferation and aggressiveness by increasing the supply of arginine for NO production." (PMID 34037347, 2021). "A definitive answer on this issue will require comprehensive analysis of paired serum and intracellular citrulline and arginine levels, alongside ARG2 and ASS1 expression, in both tumor and T cells in an in vivo setting." (PMID 33979616, 2021). "ASS1 expression was directly related to the high infiltration of the tumor stroma by iNOS expressing TILs, a feature being previously linked with good prognosis." (PMID 34344457, 2021). "The results of this analysis indicated that ASS1 expression was lower in tumor tissue than peritumoral tissue from Korean HCC patients." (PMID 33838671, 2021). "A multivariate analysis of stage, tumor ASS1, and CAF-ARG2 expression showed that ASS1 and stage were independent prognostic variables (p = 0.01, HR 0.46 [0.2–0.8] and p = 0.0001, HR = 3.8 [95% CI 1.9–7.8], respectively)." (PMID 34344457, 2021). "We employed a combination of computational, genetic, and metabolomic tools along with in vivo animal models to establish a tumor-suppressive role for ASS1 and ASL in ccRCC." (PMID 34861885, 2021). "Activation of the PI3K/AKT pathway is important to offset the tumor-suppressing effect of ASS1, known to be a suppressor of AKT activation." (PMID 33664852, 2021). "Consistent with their tumor inhibitory potency, LM-2I had stronger effect on ASS1 activation than SPA." (PMID 33859183, 2021).
tumor (continued). "Our studies demonstrate that SPA and LM-2I act as ASS1 agonists, which interact with and activate ASS1, leading to enhanced anti-tumor activity of ASS1." (PMID 33859183, 2021). "Human T cells do not express ASS1, and chimeric antigen receptor (CAR)-T cells engineered to express ASS1 show enhanced proliferation and in vivo anti-tumor activity, indicating that inducing expression is a mechanism to tolerate arginine depletion." (PMID 33979616, 2021). "Consistent with the immunohistochemistry analysis for ASS1 expression in PDAC tumor samples, there was a range of ASS1 expression in PDAC cell lines at both the mRNA and the protein levels." (PMID 31903153, 2020). "Compared to single agents, the combination of PAN and ADI-PEG20 showed better efficacy in suppressing ASS1-low PDAC tumor growth in mouse xenograft models." (PMID 31903153, 2020). "In this study, we explored the clinical implications of ASS1 expression in PDAC with immunohistochemistry analyses of PDAC patient tumor samples." (PMID 31903153, 2020). "An arginase inhibitor therefore has potential to be effective in combination with ADI-PEG20 if anti-tumor T cells express ASS1 themselves and can make arginine." (PMID 35582579, 2019). "Adding ASS1P3 led to a reduction in tumor size and weight consistent with its ability to sponge miR-34a-5p, thus enhancing ASS1 expression and activity." (PMID 31000693, 2019). "These arginine auxotrophic tumor cells lack either argininosuccinate synthase 1 (ASS1) or ornithine carbamoyltransferase (OTC) expression, and thus interrupt the normal urea cycle." (PMID 31427725, 2019). "Another possibility is that ASS1 downregulation helps maintain a higher intracellular pH under acidic stress in the tumor microenvironment." (PMID 35582579, 2019). "It is possible that high levels of ASS1 support tumor proliferation and aggressiveness by increasing the supply of arginine for NO production." (PMID 30082427, 2018). "This demonstrates that, in some cases, ADI-PEG20 can alter tumor growth in an ASS1-proficient environment, similarly to what we observed with ASS1-positive HCT116 cells." (PMID 30108309, 2018). "Argininosuccinate synthase (encoded by ASS1) is an enzyme necessary for the biosynthesis of arginine, an amino acid whose abundance has previously been linked to tumor progression induced by hypoxia." (PMID 29731978, 2018). "In the untreated cohort, ASS1 expression correlated significantly with tumor size and tumor recurrence after surgery (Likelihood ratio, p<0.05)." (PMID 28187218, 2017). "ASS1 has been shown to play an important role in inhibition of tumor cell proliferation via induction of G1 arrest, as well as inhibition of tumor cell migration, invasion and tumor angiogenesis." (PMID 28187218, 2017). "In an ASS1low sarcoma in vivo model reported, ADI-PEG20 showed significant reduction in tumor growth compared to control, but a slow increase in tumor size was still observed over time and the tumor lysate showed significantly enhanced ASS1 expression." (PMID 28750681, 2017). "By univariate analysis, ASS1 expression, tumor size (greater than 2.0 cm), margin status, lymph node status and AJCC stage correlated significantly with both DFS and OS (p<0.05)." (PMID 28187218, 2017). "We harvested the tumor material after 2 months of treatment, and determined ASS1 levels in protein lysates." (PMID 27735949, 2016). "As CRC has been claimed to be an ASS1-positive tumor entity, we initially monitored ASS1 level in protein extracts from 16 established human CRC cell lines." (PMID 27689335, 2016). "We show that ADI-PEG20 inhibits HIF-signalling and hypoxia-induced NO in vitro and in two tumour models with differing ASS1-expression." (PMID 26972697, 2016).